LCN10 (lipocalin 10)
Description:
May play a role in male fertility. May act as a retinoid carrier protein within the epididymis.
Tractability: Antibody: UniProt places it where antibodies can reach, with high confidence; UniProt predicts a signal peptide or a membrane-spanning region; its Gene Ontology location is reachable by antibodies, with medium confidence.
Gene: Protein-coding gene on chromosome 9 (136,738,167 to 136,743,356, reverse strand). Ensembl gene ENSG00000187922.
Subcellular location: Secreted
Gene Ontology:
Molecular function: small molecule binding
Cellular component: extracellular region
Genetic constraint (gnomAD): Loss-of-function variants: 16 observed, 22.11 expected, observed/expected ratio (o/e) 0.72, 90% interval 0.49 to 1.1. The upper end of that interval is the gene's LOEUF score, 1.1, which puts it in group 4 of 6, group 1 being the genes least tolerant of losing a copy. Missense variants: 256 observed, 252.46 expected, observed/expected ratio (o/e) 1.01, 90% interval 0.92 to 1.12. Synonymous variants: 129 observed, 116.03 expected, observed/expected ratio (o/e) 1.11, 90% interval 0.96 to 1.29.
Homologues: Orthologues: macaque LCN10 (90% identical), rat Lcn10 (62% identical), guinea pig LCN10 (62% identical), mouse Lcn10 (62% identical), pig LCN10 (58% identical), dog LCN10 (54% identical). Paralogues in human: LCN15 (25% identical), LCN6 (20% identical), PTGDS (18% identical), LCN2 (17% identical), OBP2A (17% identical), OBP2B (16% identical), LCN12 (16% identical), LCN9 (16% identical), LCN1 (15% identical), PAEP (14% identical), LCN8 (14% identical), LCNL1 (12% identical).
Diseases named in the same sentence as LCN10 in open-access papers:
LCN10 is named in the same sentence as 15 diseases in open-access papers, as found by Europe PMC text mining. Sharing a sentence is not in itself a finding about the gene and the disease. The quoted sentences say what the papers report.
Sepsis (3 papers, 2021 to 2025). Sepsis is defined as life-threatening organ dysfunction caused by a dysregulated host response to infection. "The serum Lcn10 level is positively correlated with the incidence of myocardial dysfunction caused by sepsis." (PMID 34121925, 2021). "These analysis results demonstrate that circulating Lcn10 level may serve as an independent risk factor for mortality in patients with sepsis." (PMID 34121925, 2021). "In sepsis patients presenting with myocardial dysfunction, serum levels of lipocalin 10 (Lcn10) are often elevated at admission." (PMID 40799939, 2025). "In conclusion, this clinical observation demonstrates that the level of serum Lcn10 in patients with sepsis complicated with cardiac injury is higher than that in non-SIMD sepsis patients when they are admitted to the hospital." (PMID 34121925, 2021). "In the present study, we observed elevated serum levels of Lcn10 on admission in sepsis patients with myocardial dysfunction." (PMID 34121925, 2021). "Our findings suggest that the level of serum Lcn10 is a biomarker for the prognosis of sepsis, especially SIMD, and is worthy of further study." (PMID 34121925, 2021). "As such, the current study investigated serum Lcn10 levels in sepsis patients at the time of admission to characterize the possible correlation between Lcn10 levels and sepsis-induced myocardial dysfunction." (PMID 34121925, 2021). "Given that sepsis patients with myocardial dysfunction exhibited higher levels of circulating Lcn10, we next hypothesized that Lcn10 might be a good prognostic marker of SIMD." (PMID 34121925, 2021). "We found elevated serum Lcn10 levels on admission in sepsis patients with myocardial dysfunction." (PMID 34121925, 2021). "Considering the potential role of Lcn10 in heart failure, we hypothesized that serum Lcn10 levels may adaptively contribute to the pathogenesis of sepsis in patients who have cardiac dysfunction." (PMID 34121925, 2021). "Our study indicates that circulating Lcn10 levels may serve as a novel biomarker for the diagnosis and prognosis of myocardial dysfunction induced by sepsis." (PMID 34121925, 2021). "Lipocalin 10 (Lcn10) has recently been identified as a potential biomarker for heart failure, yet its relation to sepsis has not been investigated." (PMID 34121925, 2021).
heart failure (2 papers, 2021 to 2022). Inability of the heart to pump blood at an adequate rate to meet tissue metabolic requirements. "Recent meta-analysis data reveal that lipocalin 10 (Lcn10) is significantly downregulated in cardiac tissue of patients with heart failure but is increased in the blood of septic patients." (PMID 35757735, 2022). "However, our findings in patients were different from previous findings based on RNA sequencing data, which showed a dramatic decrease in Lcn10 RNA levels in the human right ventricle (heart failure) and left ventricle (dilated cardiomyopathy)." (PMID 34121925, 2021).
cardiomyopathy (1 paper, 2022). A disease of the heart muscle or myocardium proper. "Thus, any strategies that elevation of Lcn10 expression/activity in macrophages would possess therapeutic potential of diabetes-induced low-grade inflammation and concomitant cardiomyopathy." (PMID 35757735, 2022). "In addition, Lcn10-KO macrophages exhibit higher expression of cytokines/chemokines (i.e., IL-6, IL-1β, and CCL2) than wild-type controls, which are also major culprits for the development of cardiomyopathy during diabetes." (PMID 35757735, 2022).
cervical cancer (1 paper, 2024). A primary or metastatic malignant neoplasm involving the cervix. "Further research should focus on understanding the molecular mechanisms underlying the relationships between EPGN, LCN10, TP73, and ICI therapy, and explore their therapeutic potential in cervical cancer treatment." (PMID 38933923, 2024). "Future research is needed to clarify whether increased LCN10 expression/activity in macrophages or direct administration of recombinant LCN10 protein has therapeutic potential in cervical cancer." (PMID 38933923, 2024).
diabetes (1 paper, 2022). "In line with our above results that Lcn10-KO mice displayed exacerbated diabetes-induced cardiac dysfunction, transplantation of Lcn10-deficient bone marrow cells aggravated cardiac dysfunction of recipient mice, evidenced by a 12% decrease in fractional shortening." (PMID 35757735, 2022). "This is associated with a reduction of Lcn10 expression in macrophages, resulting in: 1) an exacerbated inflammation through disrupting Nr4a1 signal, 2) a high ratio of pro-/anti-inflammatory macrophage population accumulated in the heart during diabetes." (PMID 35757735, 2022). "Given the profound effects of macrophages in diabetes-induced cardiac dysfunction, we aimed to determine the role of Lcn10 in macrophages during T2D." (PMID 35757735, 2022). "In the present study, we have elucidated that Lcn10 plays a critical role in the regulation of macrophage polarization and diabetes-induced cardiac dysfunction." (PMID 35757735, 2022). "Taken together, these results suggest that Lcn10-KO hematopoietic cells are sufficient to exacerbate diabetes-induced cardiac dysfunction, mainly by triggering more infiltration of pro-inflammatory macrophages in the diabetic heart." (PMID 35757735, 2022). "We were curious to explore whether Lcn10 is involved in diabetes-induced metabolic stress." (PMID 35757735, 2022). "Therefore, reduction of Lcn10 expression observed in diabetic macrophages may be responsible for the pathogenesis of diabetes-induced cardiac dysfunction." (PMID 35757735, 2022). "However, to our knowledge, the functional role of Lcn10 has never been investigated in macrophages or diabetes." (PMID 35757735, 2022).
diabetic cardiomyopathy (1 paper, 2022). Diabetic cardiomyopathy is a disorder of the heart muscle in people with diabetes. "More importantly, adoptive transfer of Lcn10-KO bone marrow cells into X-ray irradiated mice further validate such critical contributions of pro-inflammatory macrophages and their released cytokines/chemokines to the pathogenesis of diabetic cardiomyopathy." (PMID 35757735, 2022).
dilated cardiomyopathy (1 paper, 2021). Cardiomyopathy which is characterized by dilation and contractile dysfunction of the left and right ventricles. "Moreover, a meta-analysis found that Lcn10 gene expression was downregulated in three individual analyses of human left ventricle tissues from patients with dilated cardiomyopathy." (PMID 34121925, 2021).
Infertility (1 paper, 2024). "The transgenic lines in Lcn5, Lcn6, Lcn8, and Lcn10 were knocked out simultaneously, or Lcn5, Lcn6, Lcn8, Lcn10, and Lcn9, when silenced synchronously, showed subfertility and infertility in most cases." (PMID 38785936, 2024).
Insulin resistance (1 paper, 2022). Increased resistance towards insulin, that is, diminished effectiveness of insulin in reducing blood glucose levels. "Collectively, these data demonstrate that Lcn10 deficiency leads to aggravated insulin resistance and cardiac dysfunction under diabetic conditions." (PMID 35757735, 2022). "Utilizing both in vitro and in vivo approaches, we found that Lcn10 deficiency promotes macrophage polarization toward a pro-inflammatory phenotype by disrupting the Nr4a1 signaling pathway, leading to exacerbated cardiac dysfunction and insulin resistance under T2D conditions." (PMID 35757735, 2022). "Next, using a global Lcn10-knockout (KO) mouse model to induce type-2 diabetes (T2D), we observed that loss of Lcn10 promoted more pro-inflammatory macrophage infiltration into the heart, compared to controls, leading to aggravated insulin resistance and impaired cardiac function." (PMID 35757735, 2022).
type-2 diabetes (1 paper, 2022). "Together, these findings indicate that loss of Lcn10 skews macrophage polarization to pro-inflammatory phenotype and aggravates cardiac dysfunction during type-2 diabetes through the disruption of Nr4a1-mediated anti-inflammatory signaling pathway in macrophages." (PMID 35757735, 2022).
cancer (1 paper, 2024). A tumor composed of atypical neoplastic, often pleomorphic cells that invade other tissues. "As PD-L1 expression is commonly used as a criterion for determining whether cancer patients should undergo ICI treatment, we examined the correlation between PD-L1/PD-1 expression levels, risk scores, and the expression of EPGN, LCN10, and TP73." (PMID 38933923, 2024).
infection (1 paper, 2021). The state of being infected such as from the introduction of a foreign agent such as serum, vaccine, antigenic substance or organism. "Thus, we speculate that Lcn10, like Lcn2, might be stimulated by inflammation or infection playing a role in the regulation of acute cardiac injury." (PMID 34121925, 2021).
metabolic disorders (1 paper, 2022). "However, the functional role of Lcn10 in cardiac inflammation triggered by metabolic disorders has never been investigated." (PMID 35757735, 2022).
tumor (1 paper, 2024). "Due to the pivotal roles of EPGN, LCN10, and TP73 in the TIME, we conducted an analysis of immune cell profiles in CESC to investigate the connection between IRGPI and the composition of tumor-infiltrating immune cells." (PMID 38933923, 2024).
LCN10 also shares sentences with these, for which no sentence is quoted: inflammatory bowel disease (1 paper).